INS (insulin)
Diseases named in the same sentence as INS in open-access papers (continued):
Sharing a sentence is not in itself a finding about the gene and the disease.
Insulin resistance (continued). "Normal pregnancy is characterized by physiological insulin resistance that begins in the second trimester and peaks in the third trimester, which causes increased insulin secretion." (PMID 29854818, 2018). "It is caused by an imbalance between insulin resistance and secretion, and occurs when pancreatic β-cells fail to keep up with insulin production in the face of the increasing insulin resistance during pregnancy." (PMID 30190548, 2018). "The reduction in weight gain exerted by vitamin D supplementation represents another important effect contributing to preserve local and systemic insulin sensitivity, being obesity a main causative factor for the development of insulin resistance." (PMID 29342166, 2018). "There is a strong evidence to suggest that hepatic steatosis and insulin resistances are driven by obesity-induced adipokines, and the association between insulin resistance and hepatic steatosis has been established." (PMID 30291527, 2018). "Previous study showed a pathological elevation of asprosin in human and mice with insulin resistance, and its loss of function via immunologic or genetic methods has a profound glucose- and insulin-lowering effect in mice." (PMID 29743813, 2018). "When chronically stimulated, beta cell function deteriorates, and insufficient insulin secretion, especially when coupled with insulin resistance, causes glucose elevation and type 2 diabetes." (PMID 29497784, 2018). "Metabolic syndrome is associated with aging, obesity, oxidative stress, insulin resistance, increased blood glucose, impaired glucose tolerance, increased insulin, decreased HDL, increased triglycerides, and increased LDL." (PMID 29321828, 2018). "Increases in circulating TNF-α are associated with peripheral insulin resistance, increased plasma glucose and insulin levels before the onset of T2D, whereas the increased fasting glucose level induced by obesity can be prevented by TNF-α deficiency." (PMID 30114249, 2018). "Apart from the homeostasis model assessment insulin resistance of men, serum UA was positively associated with insulin secretion and insulin resistance indexes both in men and women." (PMID 29568712, 2018). "Accordingly, the expression of some of the common insulin resistance-associated genes, including Vitamin D receptor (Vdr), was found to be reduced by treating cells with Rosiglitazone, which is normally used as an insulin-sensitising agent in T2D." (PMID 30205460, 2018). "As indicated in previous studies, our findings suggested inverse associations of serum 25(OH)D with fasting insulin and insulin resistance." (PMID 29739382, 2018). "Insulin promotes lipogenesis but, on the other hand, insulin resistance is associated with increased lipogenesis in the liver." (PMID 30013137, 2018). "Participants who achieved ≥5% weight loss had significantly lower fasting insulin, AUC insulin, and insulin resistance as measured by HOMA-IR." (PMID 29587682, 2018). "The occurrence of insulin resistance increases with aging and when insulin secretion capacity cannot increase enough to compensate for insulin resistance, aged people become susceptible to T2DM." (PMID 30380669, 2018). "Insulin resistance, the inability of cells to efficiently respond to a normal dose of insulin, is caused by impaired insulin signaling and postreceptor intracellular defects." (PMID 30574122, 2018). "Mitochondrial oxidants appear to play a causal role in insulin resistance because pharmacological or genetic (3, –, 5) scavenging of these oxidants has been shown to improve insulin action in adipose and muscle tissue." (PMID 29599292, 2018). "Insulin resistance (IR) is a hallmark for the progression of type II diabetes and causes an incomplete uptake of circulating plasma glucose due to impaired insulin secretion and/or receptor signaling." (PMID 29049981, 2018).
Insulin resistance (continued). "Hyperinsulinemia associated with increased insulin resistance is a demand for insulin secretion, and this event thought to reflect increased secretory capacity from the β-cells as a compensatory response for reducing blood glucose level during T2DM." (PMID 30116491, 2018). "The serum high molecular weight adiponectin was negatively associated with the insulin level and insulin resistance in the women exposed to SHS." (PMID 30356972, 2018). "Wang and colleagues also reported that higher intake of added sugars (10 g/day) from only liquid foods was linked to higher fasting glucose and fasting insulin, as well as increased insulin resistance." (PMID 29419785, 2018). "Adipocyte dysfunction in obesity is commonly associated with impaired insulin signalling in adipocytes and insulin resistance." (PMID 30160359, 2018). "This impaired glucose metabolism was also associated to insulin resistance as observed by higher plasma levels of insulin and C-peptide (P < 0.05)." (PMID 29323186, 2018). "Increased liver ceramide levels have also been associated with the development of hepatic insulin resistance due to ceramides can attenuate insulin signaling in liver and skeletal muscle by reducing GLUT4 translocation and glucose uptake." (PMID 30011790, 2018). "The syndromes of insulin resistance are caused by abnormal responses of human tissues (such as the muscle, liver, adipocyte, and central nervous system tissues) to insulin, thereby inducing dysfunctions in glucose and lipid metabolism." (PMID 30135362, 2018). "The inflammasome, which is activated by ER stress, alters insulin sensitivity and is activated during inflammation, causing insulin resistance." (PMID 30134566, 2018). "PTP1B is a negative regulator of insulin signaling, and its high expression is implicated in insulin resistance." (PMID 29786669, 2018). "The pathogenesis of T2DM involves the development of a relative deficiency in insulin secretion and insulin resistance." (PMID 29743959, 2018). "T2DM is characterized by abnormal insulin secretion, associated with varying degrees of insulin resistance, caused by a combination of genetic and acquired factors that impair β-cell function and tissue insulin sensitivity." (PMID 29723228, 2018). "Weight loss related to improved insulin resistance and insulin sensitivity has been reported in diet-induced obese rats in which changes in the size of adipocytes and reduction in fat tissue were observed." (PMID 29615982, 2018). "Insulin resistance, a hallmark of type 2 diabetes (T2D), refers to impaired insulin sensitivity and glucose uptake of target tissues (liver, skeletal muscle, and adipose tissue)." (PMID 30356686, 2018). "Galectin-12-deficient obese mice also show less insulin resistance/glucose intolerance than do wild-type obese mice so the insulin sensitivity and the glucose tolerance are increased." (PMID 29950926, 2018). "Vitamin D deficiency has previously been associated with insulin resistance and type 2 diabetes given its role in supporting insulin secretion and pancreatic β-cell function." (PMID 29925344, 2018). "In fact, the susceptibility to develop insulin resistance and the insulin response to stimuli that physiologically improve or compromise insulin sensitivity are different in the two sexes." (PMID 30420884, 2018). "The differences between T1DM and T2DM in terms of prevalence, disease mechanism (deficiency of insulin versus insulin resistance), age of onset, typical conformation of the patient and the treatment are well known." (PMID 30149797, 2018). "Cardiometabolic risk encompasses a cluster of risk factors that predispose individuals to type 2 diabetes and premature CVD, associated with disrupted insulin signalling and largely driven by insulin resistance." (PMID 29484207, 2018). "Weight loss improves insulin resistance by increasing hepatic insulin sensitivity and decreasing endogenous glucose production." (PMID 29948870, 2018).
Insulin resistance (continued). "A subset of T2D GWAS signals are known to influence T2D risk through a primary effect on insulin secretion, whilst others act primarily through insulin resistance." (PMID 29412141, 2018). "Hyperinsulinemia and insulin resistance are associated with low SHBG levels, suggesting that insulin level and/or insulin resistance is suppressive to SHBG production." (PMID 30057912, 2018). "In T2D, peripheral insulin resistance in target tissues (including skeletal muscle, adipose tissue and liver coupled with hypersecretion of insulin) typically precedes eventual β-cell loss." (PMID 30618774, 2018). "Our experiments showed that excessive intake of fats exacerbated aging-related loss of muscle weight accompanied by insulin resistance, whereas the intake of GTEs ameliorated insulin signaling in skeletal muscle and alleviated muscle weight loss in SAMP8 mice." (PMID 29630667, 2018). "A number of studies show that the risk of insulin resistance is reduced and/or insulin sensitivity is increased when fiber is consumed abundantly." (PMID 29461482, 2018). "T2D is characterized by hyperglycemia caused by insulin resistance in peripheral tissues and defects in insulin secretion, metabolic dysfunction and death of pancreatic beta cells." (PMID 30386256, 2018). "Insulin resistance is a hyperinsulinic condition in which insulin reduces blood glucose inadequately, causing higher sugar levels in plasma." (PMID 30337946, 2018). "This study underscores the significance of insulin signaling in brain bioenergetics and function and helps recognize deficits in diseases associated with insulin resistance." (PMID 30235271, 2018). "Insulin resistance in obese individuals causes larger amounts of insulin to be secreted in order to maintain glucose metabolism." (PMID 29986666, 2018). "Type 2 diabetes generally develops in adults, and is caused by a failure to properly respond to insulin, called insulin resistance, and/or by impaired insulin secretion due to β-cell dysfunction/loss." (PMID 29518025, 2018). "We identified a rare (minor allele frequency 0.05%) synonymous variant in CRLS1 (rs149380663) that is positively associated with multiple indicators of insulin resistance and negatively associated with measures of insulin sensitivity." (PMID 29861389, 2018). "The report indicates that butyrate treatment improves insulin sensitivity by decreasing blood lipids such as triglycerides, cholesterol, and total fatty acids considered as critical factors causing insulin resistance." (PMID 30538991, 2018). "T2DM is characterized by insulin resistance or impaired insulin secretion often in association with obesity which causes insulin resistance through secretion of various adipocyte-derived proteins." (PMID 30069271, 2018). "We have shown that GWG above the median is indeed associated with increased fasting glucose, insulin resistance, and insulin secretion." (PMID 30360536, 2018). "Current research shows that insulin resistance and insulin secretion deficiency are the main pathogeneses of diabetes, and Ginkgo biloba extract (EGb) has a bidirectional role in regulating insulin secretion." (PMID 30405743, 2018). "All of the data concerning glucose/insulin were collected to establish normal ranges, as well as correlations with parameters associated with obesity/ insulin resistance." (PMID 29333728, 2018). "Increased lipid metabolism in muscle is associated with insulin resistance and therefore, many strategies have been employed to alter fatty acid metabolism and study the impact on insulin action." (PMID 30228369, 2018). "These hormones inhibit insulin, causing insulin resistance and consequently, high insulin, compromising lipid metabolism, and increasing blood cholesterol." (PMID 29642188, 2018). "Vitamin D deficiency has been implicated in decreased insulin secretion and increased insulin resistance, and more recently with the development of T2DM." (PMID 30723655, 2018).
Insulin resistance (continued). "Insulin resistance in black populations is associated with hyperinsulinemia, as a result of greater insulin secretion and reduced hepatic insulin clearance." (PMID 29669711, 2018). "Using in vitro models of insulin resistance, we provide data that can help to better understand the role of osteocalcin in the pathophysiology of insulin deficiency and the events leading to insulin-resistant states and metabolic disorders." (PMID 28866834, 2018). "Insulin stimulates lipogenesis but insulin resistance is also associated with increased hepatic lipogenesis in obesity." (PMID 30013137, 2018). "Insulin resistance is a major feature of type 2 diabetes mellitus, whereas type 1 is due to damage of pancreatic B-cells of Langerhans islets and loss of insulin." (PMID 30400348, 2018). "We also found that high levels of insulin, often used as a proxy for insulin resistance, were associated with lower BMA." (PMID 29946974, 2018). "In vivo, massive over-expression of PPARGC1A was associated with insulin resistance; however, a modest increase in expression, as seen with exercise, improves insulin sensitivity." (PMID 30540820, 2018). "Studies comparing obese insulin resistant and insulin sensitive subjects, exercise interventions in type 2 diabetes, and induction of insulin resistance in mice, all show an association between muscle C18:0 ceramide and impairments in insulin action." (PMID 30131496, 2018). "Skeletal muscle insulin resistance is defined as reduced glucose uptake in response to insulin and is implicated in the pathogenesis of many diseases, most prominently T2DM." (PMID 30250846, 2018). "T2D is increasingly recognized as a heterogeneous condition, ranging from predominantly insulin resistance with relative insulin deficiency to predominantly an insulin secretory defect with insulin resistance." (PMID 30542326, 2018). "An overload of iron can cause insulin resistance leading to increase in the production of hepatic glucose, subsequently reducing the secretion of insulin." (PMID 30364240, 2018). "A number of other complications are also associated with T2D like insulin resistance, reduced insulin secretion, hyperinsulinemia, low insulin-mediated uptake and consumption of glucose." (PMID 30545352, 2018). "There is a close inter-relation between insulin sensitivity and sympathetic activity, with insulin resistance and hyperinsulinemia being associated with SNS over activity." (PMID 30410448, 2018). "HFD-induced obesity was associated with liver insulin resistance and reduced insulin-stimulated Akt phosphorylation in livers from HFD-fed Fab-Cre mice." (PMID 29979672, 2018). "The situation is likely different in adults, where HSD decreases the IIS independently of insulin resistance, causing decreased expression of Ilp2, 3, and 5, whilst the periphery remains insulin sensitive." (PMID 29954158, 2018). "In Inter99 higher PRAL score associated with insulin resistance as estimated by lower BIGTT-Si (an OGTT-derived index of insulin sensitivity) (p = 4 × 10− 7) and Matsuda index of insulin sensitivity (p = 2 × 10− 5) as well as higher HOMA-IR (p = 0.001)." (PMID 30292239, 2018). "Obesity is strongly associated with a state of insulin resistance where tissues and organs such as adipose tissue, skeletal muscle and liver inadequately respond to insulin." (PMID 30032404, 2018). "Our data indicated that tissue‐specific effects of the Ly6Chigh monocytes and/or metabolic tissue changes predicted the development of some aspects of insulin resistance, which led us to examine the association of monocyte phenotype and insulin levels." (PMID 30548217, 2018). "In terms of glucose–insulin physiology, insulin resistance is associated with shorter LTL, and a more recent longitudinal study indicated that individuals with shorter LTL are more likely to develop insulin resistance later in life." (PMID 29335381, 2018).
Insulin resistance (continued). "Even in nondiabetic individuals, hyperinsulinemia is associated with decreases in insulin-mediated glucose uptake, as well as with a number of clinical symptoms associated with insulin resistance." (PMID 30138332, 2018). "Higher BMI, higher waist circumference, and greater insulin resistance (lower inverse fasting insulin) were associated with lower nadir SpO2 among participants with NGT." (PMID 29910773, 2018). "High D5D activity is associated with lower risk of cardiovascular incidences and also with good insulin sensitivity while a low D6D activity index is associated with a lower risk of mortality, insulin resistance, and obesity." (PMID 30103441, 2018). "Overweight/obesity is associated with insulin resistance, impaired insulin section and elevated inflammation levels." (PMID 30454043, 2018). "This adipokine is preferably expressed in visceral adipose tissue (visceral vascular stroma cells), which is negatively associated with insulin resistance and obesity, increasing the effect of insulin on the glucose metabolism." (PMID 30666216, 2018). "Gestation is associated with increasing maternal insulin resistance, as well as β-cell expansion, to account for the increased insulin needs and studies performed in pregnant rats support a role of miRNAs in this expansion." (PMID 30424584, 2018). "It means that the overactivated mTORC1 in pancreas β-cells causes an increased insulin secretion to compensate for insulin resistance, but eventually, it leads to β-cell failure." (PMID 30034573, 2018). "This uncertainty arises from temporal issues such as IMAT showing strong associations with insulin resistance before interventions, yet failing to predict improvement in insulin sensitivity with reductions in IMAT." (PMID 30254672, 2018). "T2DM can be caused by either insulin resistance or impaired insulin secretion, and is considered a component of metabolic syndrome." (PMID 30583546, 2018). "Since cerebral insulin resistance leads to increased amyloid β accumulation which causes synaptic damage, the insulin-sensitizing effect adiponectin seems desirable to preserve memory." (PMID 30002734, 2018). "It is a heterogeneous group of disorders that exhibit relative insulin deficiency and is usually associated with obesity, insulin resistance, impaired insulin secretion, and increased hepatic glucose production." (PMID 30057912, 2018). "Several studies have suggested that lipid metabolism is regulated mainly by the insulin signaling pathway, and hepatic lipid accumulation is strongly associated with insulin resistance (IR)." (PMID 30275422, 2018). "As we have already mentioned, it is important to emphasize that both nutrients and insulin activate mTOR, but the overactivated mTOR further causes insulin resistance by at least two mechanisms." (PMID 30034573, 2018). "To elucidate the mechanism underlying impaired TG homeostasis in insulin resistance state we studied the effect of insulin on GPIHBP1 protein expression in human microvascular endothelial cells (HMVEC) under flow conditions." (PMID 30408040, 2018). "Skeletal muscle is the predominant tissue of insulin-mediated glucose uptake in the postprandial state in humans; moreover, lipid accumulation in this tissue is associated with insulin resistance." (PMID 29867762, 2018). "Insulin resistance and insulin signaling pathway have been suggested to be associated with hypertension in both clinical (metabolic syndrome) and basic trials." (PMID 29961674, 2018). "The mechanisms underlying the uncoupling of insulin resistance and elevated plasma insulin warrants further investigation." (PMID 30054493, 2018). "Insulin resistance is defined as decreased insulin-stimulated glucose uptake, and is associated with inactivity, obesity, and aging." (PMID 29467962, 2018). "Percentage change in insulin or insulin resistance associated with air pollutants with corresponding 95% confidence interval (CI) was used to evaluate the risk." (PMID 30463387, 2018).